CYP1B1 (cytochrome P450 family 1 subfamily B member 1)
Diseases named in the same sentence as CYP1B1 in open-access papers (continued):
Sharing a sentence is not in itself a finding about the gene and the disease.
osteosarcoma (2 papers, 2017 to 2025). A usually aggressive malignant bone-forming mesenchymal neoplasm, predominantly affecting adolescents and young adults. "Therefore, this study aimed to characterize the expression patterns of CYP1B1 protein using immunohistochemistry in bone sarcomas, with a special focus on osteosarcoma and chondrosarcoma, and evaluate its association with relevant clinicopathological characteristics and patient outcomes." (PMID 41155673, 2025). "To investigate the biochemical and clinical value of CYP1B1 in bone sarcomas, we analyzed its expression in osteosarcoma and chondrosarcoma tissues relative to normal bone tissues." (PMID 41155673, 2025). "Transcriptomic data showed significantly lower CYP1B1 mRNA in osteosarcoma versus normal bone, suggesting post-transcriptional or translational regulation." (PMID 41155673, 2025). "In support of these conclusions, an independent analysis of RNA-seq data revealed that osteosarcoma tissues had much lower levels of CYP1B1 mRNA than normal bone tissues." (PMID 41155673, 2025). "This has been observed in osteosarcoma cell lines, where elevated CYP1B1 mRNA and protein levels result from AhR pathway activation." (PMID 41155673, 2025). "CYP1B1 was highly expressed in osteosarcomas (39, 78%) and chondrosarcomas (23, 82.1%) compared to normal tissue samples (2, 2.5%)." (PMID 41155673, 2025). "This study revealed a consistent and selective overexpression of CYP1B1 protein in bone sarcomas, particularly osteosarcoma and chondrosarcoma, compared to normal bone tissue." (PMID 41155673, 2025). "CYP1B1 was found to be significantly overexpressed in bone sarcomas (osteosarcoma, 78%; chondrosarcoma, 82.1%), whereas healthy normal bone tissues displayed minimal expression (12.5%, p < 0.001)." (PMID 41155673, 2025). "Hormonal regulation also plays a role; in osteosarcoma cell models, treatment with 17β-estradiol leads to an increase in the expression of CYP1B1." (PMID 41155673, 2025). "CYP1B1 expression was significantly correlated with age in patients below 34 years (p = 0.013), which aligns with the prevalence of osteosarcoma in adolescents and young adults." (PMID 41155673, 2025). "CYP1B1 expression was markedly decreased in osteosarcoma compared to normal samples (mean log2(count + 1): 3.62 vs. 6.34), corresponding to an approximate six-fold decrease on the original count scale." (PMID 41155673, 2025). "Results of microarray and subsequent PCR analysis did reveal that estrogen metabolizing and synthesizing enzymes, such as CYP1B1 and aromatase, were increased by 3-MC in hFOB and osteosarcoma cell line, MG-63." (PMID 29039776, 2017). "The high connectivity and modular structure of the CYP1B1 PPI network highlight its central role in detoxification, estrogen metabolism, and drug response pathways, which are critical in osteosarcoma and chondrosarcoma progression and drug resistance." (PMID 41155673, 2025). "Only a small osteosarcoma cohort without any chondrosarcoma cases had transcriptomic data, and CYP1B1 protein expression was evaluated only by immunohistochemistry without orthogonal validation." (PMID 41155673, 2025).
psoriasis (2 papers, 2022 to 2025). An autoimmune condition characterized by red, well-delineated plaques with silvery scales that are usually on the extensor surfaces and scalp. "Furthermore, integration with psoriasis-related gene data revealed five overlapping genes, with CYP1A1 and CYP1B1 emerging as core targets." (PMID 40864793, 2025). "This analysis revealed a significant interaction between CYP1B1 and CYP1A1, suggesting that these proteins may represent key molecular targets through which Inulae Flos exerts its potential therapeutic effects in psoriasis." (PMID 40864793, 2025).
skin cutaneous melanoma (2 papers, 2020 to 2023). "In addition, CYP1B1 expression was positively correlated with both IDO1 and TDO2 expression in skin melanoma (SKCM), squamous lung carcinoma (LUSC), diffuse large B-cell lymphoma (DLBC) and pancreatic adenocarcinoma (PDAC)." (PMID 32782249, 2020).
Stroke (2 papers, 2024 to 2025). Sudden impairment of blood flow to a part of the brain due to occlusion or rupture of an artery to the brain. "Our findings demonstrated that TLR2 and CYP1B1 overexpression induced depressive-like behaviors in post-stroke rats." (PMID 41164411, 2025). "So, it is believed that CYP1B1 is a key protein that regulates estradiol levels after stroke." (PMID 38376054, 2024).
triple-negative breast carcinoma (2 papers, 2020 to 2022). An invasive breast carcinoma which is negative for expression of estrogen receptor (ER), progesterone receptor (PR), and human epidermal growth factor receptor 2 (HER2). "Therefore, the presence of homozygous variant genotype (GG) and variant allele (G) of CYP1B1 4326C>G polymorphism of CYP1B1 was associated with lower response rates, shorter progression-free survival, and an overall decrease in patient survival among patients with triple-negative breast cancer." (PMID 33185690, 2020). "Here, we report on in vitro studies in triple-negative breast cancer cell lines, where knockdown (KD) of CYP1B1 was used to determine the influence of its expression on invasive cell phenotypes." (PMID 36077068, 2022).
acute leukemia (1 paper, 2015). A clonal (malignant) hematopoietic disorder with an acute onset, affecting the bone marrow and the peripheral blood. "Genotype frequencies of CYP1B1, CYP3A5, GSTT1, GSTM1 and SULT1A1 in females and early age acute leukemia, Brazil, 2000–2012." (PMID 25992585, 2015). "Genotype frequencies of CYP1B1, CYP3A5, GSTT1, GSTM1 and SULT1A1 in males and early age acute leukemia, Brazil, 2000–2012." (PMID 25992585, 2015).
acute monocytic leukemia (1 paper, 2025). Acute monoblastic leukemia (AML-M5), is one of the most common subtypes of acute myeloid leukemia (AML) that is either comprised of more than 80% of monoblasts (AML-M5a) or 30-80% monoblasts with (pro)monocytic differentiation (AML-M5b). "Given the pivotal role of macrophages in the immune responses to both T2DM and TB, we employed a human acute monocytic leukemia cell (THP-1) model to investigate the regulatory effects of the cross-talk genes CHPT1, SERPING1, and CYP1B1 in inflammatory responses." (PMID 40917351, 2025).
adrenal cortical carcinoma (1 paper, 2023). "To investigate whether CYP1B1 may also be a minor pregnenolone synthesis pathway in peripheral steroidogenic cells, we examined the effects of CYP1A1/CYP1B1 inhibitors and siRNA knockdown on human adrenal cortical carcinoma cells H295R-S1." (PMID 37442234, 2023).
amyloid (1 paper, 2024). "In longitudinal analysis, Cyp1b1 expression changed with aging in rTg4510 mice but not J20 mice, suggesting Cyp1b1 expression is associated with tau but not amyloid pathology." (PMID 39304655, 2024).
anaemia (1 paper, 2010). "To evaluate the risk of death we carried out a Cox regression analysis entering known prognostic baseline factors (i.e. pre-treatment PSA, anaemia, visceral metastasis) and the polymorphisms significantly associated with OS in the univariate model (i.e. CYP1B1 4326C>G polymorphism)." (PMID 20875115, 2010).
angle-closure glaucoma (1 paper, 2015). The sudden increase of intraocular pressure, resulting in pain and an abrupt decrease in visual acuity. "Nonetheless, CYP1B1-deficient mice exhibit abnormalities in their aqueous drainage system that are similar to those reported in human angle-closure glaucoma patients." (PMID 26064891, 2015). "A mouse model with mutations in both CYP1B1 and Tyr was also developed and revealed that Tyr mutation modifies the phenotype associated with inheritance of mutant orthologs of CYP1B1 and Foxc1, both of which have been shown to be involved in human angle-closure glaucoma." (PMID 26064891, 2015).
Arthritis (1 paper, 2022). Inflammation of a joint. "Among the polymorphisms found more frequently in AS patients with arthritis, JAK2 rs7857730, IL-23R rs11209008 and rs10489630, CYP1B1 rs1056836, NELL1 rs8176786, KL rs564481, MEFV rs224204, IL-2RB rs743777, and IL-1A rs1800587 have been described." (PMID 35629038, 2022).
aspergillosis (1 paper, 2024). Aspergillosis is an infection, growth, or allergic response caused by the Aspergillus fungus. "For this purpose, we evaluated the expression of genes downstream of AhR, such as cytochrome P450 family 1 subfamily A member 1 (Cyp1a1) and subfamily B member 1 (Cyp1b1) and Il22 in the lungs and colons of mice with aspergillosis and candidiasis, respectively." (PMID 38534388, 2024).
asthma (1 paper, 2018). "HTR2C, CYP1B1, CYP19A1, ESR1, ESR2, PDR, and AR are found to be interrelated to hormonal disorders; ABCC1, NQO1, TIMP1, ADRB2, and ALOX5 are associated with asthma." (PMID 29861771, 2018).
benign ovarian tumors (1 paper, 2015). "In conclusion, we demonstrated that CYP1B1 was overexpressed in human malignant OC samples and that its expression levels were significantly higher than those in benign ovarian tumors or normal ovarian tissue." (PMID 25516145, 2015). "We observed negative CYP1B1 expression in all the normal ovarian tissue samples, yet positive immunoreactivity in 13.33% of the benign ovarian tumor samples." (PMID 25516145, 2015).
benign prostatic hypertrophy (1 paper, 2017). "In contrast, weak or no epithelial CYP1B1 expression was found in benign prostatic hypertrophy (BPH) tissues with average staining scores of 0.67±0.20 (versus 2.17±0.22 in cancer tissues)." (PMID 28388569, 2017).
bladder tumors (1 paper, 2013). "Our observations clearly indicate that CYP1A1 and CYP1B1 are overexpressed in colon and bladder tumors." (PMID 24358191, 2013). "The results of our analysis corroborate with these findings, given that CYP1A1 and CYP1B1 mRNA transcripts were elevated in 80% and 60% of colon and in 65% of bladder tumors respectively." (PMID 24358191, 2013). "CYP1A1 and CYP1B1 were differentially overexpressed in colon and bladder tumors." (PMID 24358191, 2013).
bone sarcoma (1 paper, 2025). A sarcoma that arises from the bone. "These CYP1B1 expression patterns and mechanistic insights may have substantial diagnostic and therapeutic implications for bone sarcomas." (PMID 41155673, 2025). "Despite CYP1B1’s poor prognostic value, its consistent selective expression makes it a potential candidate for the development of targeted therapies for bone sarcomas." (PMID 41155673, 2025). "CYP1B1 was strongly detected in most bone sarcomas (79.5%), whereas normal samples displayed negligible expression (2 and 12.5%)." (PMID 41155673, 2025). "Collectively, these findings support the integration of CYP1B1-targeted strategies into therapeutic pipelines, pending validation in future preclinical and clinical studies, particularly for bone sarcomas." (PMID 41155673, 2025). "Moreover, there was a significant difference (p < 0.05) in CYP1B1 expression between the various bone sarcoma and normal bone tissue samples." (PMID 41155673, 2025). "Given the observed expression trends, it is critical to explore the possible regulatory mechanisms that may trigger CYP1B1 overexpression in bone sarcomas." (PMID 41155673, 2025). "By analogy to other cancers, CYP1B1 may promote bone sarcoma development via several oncogenic mechanisms." (PMID 41155673, 2025). "While the expression of certain CYPs, such as CYP3A4/5, has been investigated in bone sarcomas, the expression of CYP1B1 in bone sarcomas remains unclear." (PMID 41155673, 2025). "Interestingly, the prognostic value of CYP1B1 in bone sarcomas was not independent when analyzed using multivariate Cox regression analysis." (PMID 41155673, 2025).
brain cancer (1 paper, 2019). A primary or metastatic malignant neoplasm affecting the brain. "CYP1B1 is one of the best-known CYP450s up-regulated in multiple cancers, like breast, colon and brain cancer, and studies are in progress to use it as a therapeutic target in the treatment of cancers." (PMID 31258835, 2019).
brain injury (1 paper, 2022). Acute and chronic (see also brain INJURIES, CHRONIC) injuries to the brain, including the cerebral hemispheres, CEREBELLUM, and brain STEM. "In a previous publication we showed regulation of genes including the Cytochrome P450 family in hippocampus and cortex after penetrating traumatic brain injury (pTBI) in rats, further analysis of that material showed Cytochrome P450 1B1 (CYP1B1) to be distinctly upregulated." (PMID 35054909, 2022).
colorectal adenocarcinoma (1 paper, 2007). The most common type of colorectal carcinoma. "CYP1B1 is overexpressed in colorectal adenocarcinomas relative to normal colon tissue, and a variant with increased activity towards several substrates including sex hormones has been associated with increased risk of CRC." (PMID 17615053, 2007).
colorectal tumor (1 paper, 2013). "Moreover Gibson and colleagues demonstrated strong CYP1B1 immunoreactivity present in human colorectal tumor epithelia of 61 subjects and absence of CYP1B1 staining in normal colonic epithelia." (PMID 24358191, 2013).
Cushing syndrome (1 paper, 2024). Cushing's syndrome (CS) encompasses a group of hormonal disorders caused by prolonged and high exposure levels to glucocorticoids that can be of either endogenous (adrenal cortex production) or exogenous (iatrogenic) origin. "After the onset of the disease, according to the calculation of GSVA and GSEA, underexpression of CYP1B1 would activate the Cushing syndrome pathway, and overexpression of CYP1B1 will activate chemical carcinogenesis‐reactive oxygen species." (PMID 38376054, 2024).
delirium (1 paper, 2026). A disorder characterized by confusion; inattentiveness; disorientation; illusions; hallucinations; agitation; and in some instances autonomic nervous system overactivity. "COMT, MYD88, and CYP1B1 were identified as key candidate genes underlying opioid-associated delirium." (PMID 42307217, 2026).
epithelial dysplasia (1 paper, 2011). "Similar to a majority of the tumor tissues, the epithelial dysplasia (ED) lesion also showed significant downregulation of CYP1B1." (PMID 22114726, 2011). "CYP1B1 was found to be downregulated at the mRNA level as determined by qRT-PCR in 77.78% (28/36) of the tumor tissues in comparison to their corresponding normal tissues and an epithelial dysplasia case." (PMID 22114726, 2011). "CYP1B1 was found to be downregulated in 77.78% (28/36) tumor tissues in comparison to their corresponding normal tissues as well as in the epithelial dysplasia lesion compared to its matched normal tissue at the transcriptional level, and in 92.86% (26/28) of tumor tissues at the protein level." (PMID 22114726, 2011). "This study has investigated the expression profile of CYP1B1 in a panel of 51 OSCC cases and an epithelial dysplasia case." (PMID 22114726, 2011). "The expression profile of CYP1B1 was analysed in a panel of 51 OSCC tumors, their corresponding normal tissues, an epithelial dysplasia lesion and its matched normal tissue by qRT-PCR, Western blotting and Immunohistochemistry." (PMID 22114726, 2011).
heart failure (1 paper, 2018). Inability of the heart to pump blood at an adequate rate to meet tissue metabolic requirements. "Our data suggest the potential of repurposing 2 ME as a selective CYP1B1 inhibitor for the treatment of heart failure." (PMID 29426916, 2018).
hypospadias (1 paper, 2018). Hypospadias is the displacement of the urethral meatus on the ventrum of the penis. "A significantly positive correlation was found between the mRNA expression level of SRD5A2 and that of CYP1B1 in the hypospadias group." (PMID 29080015, 2018). "A significantly higher CYP1B1 expression level and a lower AR expression level were observed in the hypospadias groups than in the phimosis group." (PMID 29080015, 2018). "The mRNA expression levels of CYP1A1 and CYP1B1 showed an extremely high correlation in both the hypospadias and phimosis groups." (PMID 29080015, 2018). "We then compared the expression levels of CYP1A1 and CYP1B1 between hypospadias and phimosis samples by quantitative RT-PCR analysis." (PMID 29080015, 2018). "In this study, using RNA samples clinically collected from preputial tissues, we first demonstrated that the expression levels of the xenobiotic exposure marker genes, CYP1A1 and CYP1B1 correlated only in hypospadias patients but not in phimosis patients." (PMID 29080015, 2018). "Negative correlations were found between the methylation level of SRD5A2, especially at the − 221 Sp1 site, and the CYP1 family mRNA expression levels (CYP1A1, p = 0.002; CYP1B1, p = 0.007) in hypospadias patients, but not in phimosis patients." (PMID 29080015, 2018).
influenza infection (1 paper, 2025). "CYP1B1 KO in mice is protective for CS-enhanced susceptibility of smokers during influenza infection." (PMID 40688072, 2025).
Jacobsen syndrome (1 paper, 2024). A multiple congenital anomaly/intellectual disability contiguous gene syndrome caused by partial deletion of the long arm of chromosome 11. "Most importantly, the use of WES has allowed us to both assess variants in known ASD genes (i.e., CYP1B1, ITPR1, MAB21L1, PXDN, and PITX2) and to identify rarer phenotypes (i.e., MIDAS, oculogastrointestinal-neurodevelopmental syndrome and Jacobsen syndrome)." (PMID 38459225, 2024).
liver disease (1 paper, 2026). "Benzo[a]pyrene led to Metabolic dysfunction-associated steatotic liver disease by promoting hepatic lipid accumulation through the CYP1B1-mediated suppression of lipophagy." (PMID 41503284, 2026).
mammary adenocarcinoma (1 paper, 2013). "Two early reports from the group of Liehr and Ricci demonstrated overexpression of CYP1B1 activity in mammary adenocarcinoma and human uterine myoma, compared to normal breast tissue and surrounding myometrial tissue respectively." (PMID 24358191, 2013).
metastatic cancer (1 paper, 2025). A carcinoma which has spread from the original site of growth to another anatomic site. "CYP1B1 promotes metastatic cancer cell growth in a fatty acid-dependent manner." (PMID 40108724, 2025).
microcephaly (1 paper, 2024). A congenital or acquired developmental disorder in which the circumference of the head is smaller than normal for the person's age and sex. "In family HOU1842, the additional pathogenic variant in CYP1B1 (HGNC:2597) was identified in BAB4134, who was initially diagnosed with microcephaly and DD and ID." (PMID 38622594, 2024).
nodular goiter (1 paper, 2011). Goiter characterized by discrete tissue mass(es) that may or may not produce thyroid hormones. "CYP1B1 was significantly lowly methylated in nodular goiter compared with normal thyroid tissues in the present study, suggesting that its aberrant expression may play a key role in in the pathogenesis of nodular goiter." (PMID 21988780, 2011). "Among of them, there was a significantly distinct methylation profiling of ABCB4, CYP1B1 and CYP24A1 and SLC1A2 between nodular goiter and normal thyroid tissues (P < 0.05)." (PMID 21988780, 2011).
normal tension glaucoma (1 paper, 2009). "Results suggested that genetic variation in five of the candidate genes (RDX, SNX16, OPA1, SOD2 and CYP1B1) is unlikely to confer major risk to develop normal tension glaucoma in the German population." (PMID 19754948, 2009).
optic neuropathies (1 paper, 2024). "In addition to these patients with possible inherited optic neuropathies, six other patients (20.0% of patients with an alteration of the GCC) carried suspected unique pathogenic variants in six recessive genes (DPYD, AGXT, CYP1B1, ACO2, LTBP2 and FDXR)." (PMID 38796496, 2024). "The susceptibility variants identified in the other six patients were not firmly responsible on their own for a genetic form of optic neuropathy since they were found in recessives genes (DPYD, ACO2, AGXT, CYP1B1, LTBP2 and FDXR) with a single affected allele." (PMID 38796496, 2024).